PACS2 (phosphofurin acidic cluster sorting protein 2)
Diseases named in the same sentence as PACS2 in open-access papers (continued):
Sharing a sentence is not in itself a finding about the gene and the disease.
endothelial dysfunction (1 paper, 2022). In vascular diseases, endothelial dysfunction is a systemic pathological state of the endothelium (the inner lining of blood vessels) and can be broadly defined as an imbalance between vasodilating and vasoconstricting substances produced by (or acting on) the endothelium. "These endothelial dysfunctions caused by FAO inhibition cannot be offset by PACS2 knockdown, indicating that FAO works downstream of PACS2." (PMID 35865947, 2022).
glomerulosclerosis (1 paper, 2022). A hardening of the kidney glomerulus caused by scarring of the blood vessels. "In conclusion, PACS2 participates in renal vascular hyperpermeability and glomerulosclerosis by regulating the FAO of diabetic mice." (PMID 35865947, 2022). "Therefore, knocking down PACS2 can alleviate vascular barrier damage and glomerulosclerosis by enhancing the FAO ability." (PMID 35865947, 2022). "Mice lacking PACS2 improved vascular leakage and glomerulosclerosis under high fat diet." (PMID 35865947, 2022).
heart failure (1 paper, 2022). Inability of the heart to pump blood at an adequate rate to meet tissue metabolic requirements. "For example, PACS2 contributed to cardiomyocyte apoptosis in myocardial infarction and heart failure." (PMID 35951762, 2022).
injury (1 paper, 2022). Damage inflicted on the body as the direct or indirect result of an external force, with or without disruption of structural continuity. "As we all know, the triglycerides themselves serve primarily a storage function with toxicity deriving mainly from FFA, FC, CE, ceramides, etc., indicating PACS-2 may have a renoprotective role from lipid-related kidney injury in DKD." (PMID 36138342, 2022).
kidney injury (1 paper, 2022). Trauma to the kidney. "We found that tubule-specific Pacs-2 deletion markedly aggravated lipid accumulation in tubular cells by increasing the expression of SOAT1 and then regulating lipid synthesis, uptake and efflux by SOAT1/SREBPs signaling, eventually resulting in worsening albuminuria excretion and kidney injury." (PMID 36138342, 2022).
liver steatosis (1 paper, 2022). "Moreover, reduction of Pacs-2 levels also results in improved insulin sensitivity and improved liver steatosis in ob/ob mice." (PMID 36138342, 2022).
microcephaly (1 paper, 2025). A congenital or acquired developmental disorder in which the circumference of the head is smaller than normal for the person's age and sex. "Pathogenic variant sites on PACS1 and PACS2 have been associated with neurodevelopmental delay, seizures, behavioral issues, and microcephaly." (PMID 40533307, 2025).
myocardial disorder (1 paper, 2023). A disorder that affects the muscle tissue of the heart. "Pacs2 cKO mice in NN exhibited significantly increased myocardial disorder and fibrosis." (PMID 36968068, 2023).
cancer (8 papers, 2017 to 2024). A tumor composed of atypical neoplastic, often pleomorphic cells that invade other tissues. "No information is currently available about cancer-associated mutations in PACS-2, but it is clear that the regulatory serine 437 residue would correspond to a prime candidate." (PMID 28603693, 2017). "Five core genes (ACAT1, PACS2, VDAC1, MFN1, and ATAD3A) playing critical roles in cancer were identified in this study." (PMID 36902617, 2023). "From these functions, and if restricting a cancer role to its function on the MAM, we would predict that PERK, like PACS-2 and mitofusin-2, should act as a tumor suppressor." (PMID 28603693, 2017). "PACS2 is also considered to mediate death-ligand induced apoptosis produced by tumor necrosis factor (TNF)-related apoptosis-inducing ligand (TRAIL), which in vivo is a metastasis inhibitor that kills cancer or infected cells." (PMID 38540691, 2024). "Notably, expression levels of proteins facilitating mitochondrial-ER interaction, including AKAP1, RICTOR, Rab32, PACS2, GPR75, and PEMT1, were reduced in these cancer tissues." (PMID 33614647, 2021). "Genes and AS events enrolled in the comprehensive prognostic signature included RHOT1 (ES), SH3KBP1 (AP), AGTRAP (AA), PACS2 (AP), RBPMS (AT), B3GNTL1 (AP), MOBP (AT), NPHP3 (ES), ABCC5 (RI), FKTN (ES) and FKBP8 (AA), many of which are known to play important roles in cancer biology." (PMID 32467664, 2020). "The recently demonstrated pro-apoptotic properties of PACS1 and PACS2 and their transcriptional regulation by ADA3 and PCAF suggests that the four proteins (and possibly others) constitute a novel signaling pathway that acts to suppress the formation of gastric (and possibly some other) cancers." (PMID 29670108, 2018). "Therefore, with the exception of mitofusin-2 and PACS-2, most MAM tethering regulators show no clear association with the progression of cancer or no logical connection of their expression pattern to their role as MAM tethers." (PMID 28603693, 2017).
tumor (6 papers, 2017 to 2024). "While this finding needs validation in a larger patient cohort, a selective pressure for the loss of PACS-2 expression in tumor cells could indicate that the pro-apoptotic functions of PACS-2 may dominate effects on tumor formation and growth." (PMID 29312533, 2017). "PACS-2 was equally expressed in tumor and non-tumor tissues from the colons of ApcMin/+Pacs2+/+ (control) mice as shown by western blot, and confirmed by qRT-PCR analysis." (PMID 29312533, 2017). "As EGFR signaling is highly mitogenic for intestinal epithelial stem cells, and plays essential roles in intestinal epithelial regeneration and tumor development, we have now examined the role of PACS-2 in these processes." (PMID 29312533, 2017). "Examples for such proteins are mitofusin-2 and phosphofurin acidic cluster sorting protein 2 that likely act as tumor suppressors." (PMID 28603693, 2017). "Therefore, similar to the better-characterized mitofusin-2, it is expected that PACS-2 acts as a tumor suppressor, whose absence would be indeed expected to lead to ER–mitochondria uncoupling, but this has not been determined at this point." (PMID 28603693, 2017). "β-catenin was localized to the perinuclear region in tumors, but cell membrane-associated in the surrounding non-tumor tissue, with no apparent differences between control and ApcMin/+Pacs2-/- mice." (PMID 29312533, 2017). "Similarly, the TRAIL-induced apoptosis pathway which kills diseased cells such as tumor cells or virus-infected cells can be mediated by PACS-2, where dephosphorylation of PACS-2 triggered by TRAIL promotes their recruitment and translocation of Bid to mitochondria with the subsequent cyt-c release." (PMID 36275635, 2022). "Also, a small selection of clinical material showed loss of PACS-2 in 4 out of 8 tumor samples, with PACS-2 expression being preserved in the surrounding non-tumor tissue." (PMID 29312533, 2017). "Additionally, the selective apoptosis of tumor cells and virus-infected cells induced by TNF-α requires PACS-2." (PMID 38540691, 2024). "Gross examination of isolated ileal tissue from control and ApcMin/+Pacs2-/- mice revealed no obvious differences in tumor load." (PMID 29312533, 2017).
neurodevelopmental disorder (3 papers, 2022 to 2024). A behavioral and cognitive disorder with onset during the developmental period that involves impaired or aberrant development of intellectual, motor, or social functions. "Since 2012, when PACS1-NDD was first characterized, deep phenotyping analysis has allowed us to establish a potential relationship with other neurodevelopmental disorders, such as the PACS2 or Wdr37 syndromes." (PMID 36077045, 2022). "Phosphofurin Acidic Cluster Sorting Protein 2 (PACS2)-related early infantile developmental and epileptic encephalopathy (EIDEE) is a rare neurodevelopmental disorder." (PMID 37189870, 2023).
genetic disease (2 papers, 2023 to 2025). "Overall, our results confirm the presence of consistent facial similarities among PACS1-, PACS2-, and WDR37-related syndromes and highlight the utility of AI-driven facial phenotyping as a complementary tool for uncovering clinically relevant relationships in ultra-rare genetic disorders." (PMID 40869285, 2025).
neurological disorder (2 papers, 2025). "Indeed, PACS2 was included in this loss, a gene linked to neurological disorders and perturbed in other RC14 cases." (PMID 40725393, 2025). "Recent work revealed strong similarities between PACS1-NDD, PACS2 syndrome and the recently identified WDR37 syndromic neurological disorder." (PMID 39999877, 2025).
cardiovascular diseases (1 paper, 2022). "PACS2 is associated with Ca2+ transfer in mitochondria, and it has been involved in the regulation of cardiovascular diseases." (PMID 35951762, 2022).
infection (1 paper, 2023). The state of being infected such as from the introduction of a foreign agent such as serum, vaccine, antigenic substance or organism. "We obtained cardiomyocytes with stable overexpression of Pacs2 through lentiviral vectors (LVVs) infection." (PMID 36968068, 2023).
PACS2 also shares sentences with these, for which no sentence is quoted: Obesity (4 papers); metabolic disorders (3); autism spectrum disorder (2); ciliopathies (2); developmental delay (2); Alzheimer disease (1); Bardet-Biedl syndrome (1); Cerebral atrophy (1); chronic gastritis (1); Corneal opacity (1); gastric cancer (1); metabolic syndrome (1); mitochondrial DNA depletion syndrome 9 (1); myocardial hypertrophy (1); myocardial infarction (1); Neurodevelopmental delay (1); prostate carcinoma (1); renal fibrosis (1); Senior-Loken syndrome (1); Sepsis (1); Usher syndrome (1).